CASQ2 (calsequestrin 2)
Diseases named in the same sentence as CASQ2 in open-access papers (continued):
Sharing a sentence is not in itself a finding about the gene and the disease.
Immunodeficiency (1 paper, 2006). Failure of the immune system to protect the body adequately from infection, due to the absence or insufficiency of some component process or substance. "Our data also supports the fact that immunodeficiency is correlated with altered calcium ion binding (UTRN, ID: AA676840; CDH6, ID: AA421819, CASQ2, ID: AA055163) and also is influenced by calcium- activated chloride channels (CLCA2, ID: AI675394) of host cells." (PMID 16956415, 2006).
Sotos syndrome (1 paper, 2024). Sotos syndrome is a rare multisystemic genetic disorder characterized by a typical facial appearance, overgrowth of the body in early life with macrocephaly, and mild to severe intellectual disability. "Recently, a young individual with Sotos syndrome and a pharmacologically induced type 1 Brugada ECG pattern was shown to have a heterozygous mutation of CASQ2." (PMID 39062601, 2024). "Furthermore, heterozygous mutations of the CASQ2 gene have been described as a VUS in a patient with BrS and in a young subject with a pharmacologically induced type 1 Brugada ECG pattern and Sotos syndrome." (PMID 39062601, 2024).
tumor (8 papers, 2020 to 2025). "We also analyzed the association between CASQ2 and clinicopathological variables in 482 cases of TCGA and found that the CASQ2 level significantly correlated with T stage, molecular subtype, and tumor shape." (PMID 34743414, 2022). "To determine whether HIF1α expression in the tumor microenvironment is related to CASQ2 overexpression, we checked HIF1α and cancer‐associated fibroblast markers, FSP1 and αSMA, after indirect culture with stromal WI‐38 fibroblasts." (PMID 34743414, 2022). "This could indicate the association of TPM1, CRYAB, and CASQ2 with tumor progression." (PMID 31991631, 2020). "As the level of CASQ2 mRNA showed a significant correlation with the spatial tumor shape, we examined the gross tumor shape in orthotopic mouse tumors." (PMID 34743414, 2022). "Moreover, CASQ2‐overexpressing tumor cells showed a stronger expression of vimentin than the control cells." (PMID 34743414, 2022). "CASQ2 is a potential regulator of the tumor–microenvironment interaction." (PMID 34743414, 2022). "As the in vivo microenvironment is known to induce substantial changes in the protein expression of many cancer cell lines, this finding of the preferential expression of CASQ2 in TME in vivo suggested the involvement of this protein in tumor–stroma interactions during breast tumorigenesis." (PMID 34743414, 2022). "The level of CASQ2 showed a modest association with tumor size, but not with nodal involvement and survival rate." (PMID 34743414, 2022). "CASQ2 was identified through correlation analysis of tumor three‐dimensional shapes." (PMID 34743414, 2022). "However, we observed that despite their fibroblast‐like morphology, CASQ2‐overexpressing tumor cells still showed positive expression of cytokeratin, suggesting an epithelial lineage." (PMID 34743414, 2022). "Similarly, CASQ2‐overexpressing tumors contain more mesenchymal and spindle‐shaped tumor cells compared with control tumors." (PMID 34743414, 2022). "Additionally, CASQ2 upregulated HIF1α expression in both tumor cells and cocultured fibroblasts." (PMID 34743414, 2022). "Indeed, several downstream targets of MEF2 involved in muscle structure and function were among the top FoxP1 target genes repressed in response to tumour burden, including Casq1, Casq2, Lmod3, Ky, and Mef2c —suggesting that FoxP1 up‐regulation disrupts MEF2 transcriptional activity." (PMID 33527776, 2021). "Interestingly, FAM110D and CASQ2 were overexpressed in tumor samples, whereas a higher level of them represented longer OS time, indicating such underlying mechanism as stemness characteristic might lie in their prognostic value." (PMID 34409040, 2021). "The serially transplanted tumor exhibited more spindle‐like tumor cells and higher expression of αSMA and FSP1 in the fibroblasts around the CASQ2‐expressing cancer cells." (PMID 34743414, 2022). "We found that CASQ2‐overexpressing Hs578T and MDA‐MB‐231 cells exhibited significantly increased tumor growth rates compared with the control cells." (PMID 34743414, 2022). "More specifically, some tumors showed spatial heterogeneity in the expression of CASQ2, whereas its expression was specifically induced in tumor cells but not in the adjacent normal mammary epithelial cells in other cases." (PMID 34743414, 2022). "On the other hand, TPM1, CASQ2, and CRYAB have low expression in BCa samples, which may indicate that they could serve as tumor suppressors." (PMID 31991631, 2020).
cancer (3 papers, 2020 to 2022). A tumor composed of atypical neoplastic, often pleomorphic cells that invade other tissues. "CASQ2 overexpression induced cancer‐associated fibroblast characteristics along with increased hypoxia‐inducible factor 1α (HIF1α) expression in stromal fibroblasts." (PMID 34743414, 2022). "Interestingly, we observed that CASQ2 activated the features of cancer‐associated fibroblasts in the cocultured fibroblasts." (PMID 34743414, 2022). "Furthermore, CASQ2 upregulated genes associated with mesenchymal cell differentiation, which is another feature of metaplastic carcinoma." (PMID 34743414, 2022). "In WI‐38 fibroblasts, there was significant upregulation of HIF1α when the cells were cocultured with the CASQ2 o/e cancer cells." (PMID 34743414, 2022). "Next, we performed the GSEA using TCGA data stratified with CASQ2 level and observed that the CASQ2 level was associated with calcium signaling, hematopoietic cell lineage, ECM receptor interaction, cell adhesion molecule, and cancer‐related pathways." (PMID 34743414, 2022). "We also observed that the overexpression of CASQ2 resulted in enhanced mammosphere formation, which is a measure of cancer stem cell phenotype." (PMID 34743414, 2022). "Interestingly, when cancer cells were orthotopically injected into murine mammary fat pads, the resulting tumors were frequently positive for the expression of CASQ2." (PMID 34743414, 2022). "Based on these results, we tested whether the overexpression of CASQ2 might affect the phenotype of cancer cells under hypoxia using a hypoxic chamber in vitro." (PMID 34743414, 2022). "The present study highlights an up to now unrecognized possible role of CASQ2 in cancer (BCa)." (PMID 31991631, 2020). "Highly expressed CASQ2 and PDK4 were reported to be significantly correlated with poor OS and disease-free survival in cancer patients." (PMID 33833937, 2021).
cardiac disease (3 papers, 2014 to 2020). "For four of these loci, the top gene according to OPEN had been shown to be mutated in DCM (PLN, ACTN2, TNNT2, TTN), while for two others, the top gene was known to be mutated in HCM (MYL2) or an arrhythmogenic form of cardiac disease (CASQ2)." (PMID 25633252, 2014). "Specificity of cardiac disease seen with Casq2 mutants is likely due to the tissue-specific expression patterns of the paralogues." (PMID 33093545, 2020).
genetic disease (2 papers, 2017 to 2019). "CPVT comprises heterogeneous genetic diseases, including mutations in ryanodine receptor type 2 (RyR2), calsequestrin 2 (CASQ2), triadin, or calmodulin." (PMID 28219898, 2017). "CPVT is a heterogeneous genetic disease, including autosomal dominant mutations in ryanodine receptor type 2 (RyR2, CPVT1), autosomal recessive mutations in calsequestrin 2 (CASQ2, CPVT2), and more rarely mutations in triadin or calmodulin." (PMID 32009964, 2019).
infection (2 papers, 2016 to 2017). The state of being infected such as from the introduction of a foreign agent such as serum, vaccine, antigenic substance or organism. "AAV9 efficiently infected CMs as demonstrated by real-time PCR amplification of the RFP reporter gene and by epifluorescence; infection of mutated HO-CMs induced overexpression of CASQ2 gene and restoration of expression of the protein, as in CMs differentiated from control iPSCs." (PMID 27711080, 2016). "HiPSC-CMs infection with AAV carrying the wild-type CASQ2 gene revealed to be sufficient to restore the physiological expression of CASQ2 protein, and to observe decrease in the percentage of DADs following adrenergic stimulation as well as normalization of Ca2+ transient amplitude and Ca2+ sparks." (PMID 28573431, 2017).
myopathies (2 papers, 2025 to 2026). "Fibronectin 1, fibrinogen alpha chain, musculoskeletal embryonic nuclear protein 1, glutathione S-transferase 2, calsequestrin-2, and endoplasmin emerged as potential biological markers and their prospective roles in the pathogenesis of these myopathies are discussed." (PMID 42278140, 2026). "However, paralogs of myopathy genes are often expressed in different tissues, such as RYR1 and CASQ1, which are expressed in skeletal muscles, whereas RYR2 and CASQ2 are expressed in cardiac muscles." (PMID 39945189, 2025).
autosomal dominant disease (1 paper, 2026). Autosomal dominant form of disease. "CPVT is generally an autosomal dominant disease and is associated with mutations in the RYR2 (ryanodine receptor/calcium release channel) gene and the recessive form is associated with mutations in CASQ2 (calsequestrin)." (PMID 41062843, 2026).
CASQ2 also shares sentences with these, for which no sentence is quoted: Brugada syndrome (3 papers); cardiac arrhythmia (3); long QT syndrome 3 (2); arrhythmogenic right ventricular cardiomyopathy (1); cardiovascular diseases (1); familial hypercholesterolemia (1); fibrosis (1); hepatocellular carcinoma (1); idiopathic ventricular fibrillation (1); orbital disease (1); sick sinus syndrome (1); Tachycardia (1); type 2 diabetes mellitus (1); Vascular Ehlers-Danlos Syndrome (1); ventricular ectopy (1).